FTO (FTO alpha-ketoglutarate dependent dioxygenase)
Diseases named in the same sentence as FTO in open-access papers (continued):
Sharing a sentence is not in itself a finding about the gene and the disease.
tumor (continued). "Promisingly, FTO inhibition also shows antitumoural effects within tumour microenvironments, enhancing T cell-mediated cytotoxicity and reducing immune evasion by suppressing immune checkpoint genes." (PMID 36831575, 2023). "In this study, inhibiting AKT phosphorylation clearly inhibited tumor growth in vivo and in vitro, and the expression levels of FTO and GPX4 were downregulated." (PMID 38102129, 2023). "In xenograft models treated with gemcitabine, FTO knockdown in CFPAC-GM resulted in a relatively slow tumor growth." (PMID 37605223, 2023). "Further studies confirmed that miR-155 inhibited FTO expression and increased the global m6A levels while promoting tumour cell progression and decreasing apoptosis in an FTO-dependent manner." (PMID 37284313, 2023). "As an m6A demethylase, FTO is downregulated in PCa, and its level is negatively correlated with advanced tumour stage." (PMID 37284313, 2023). "To explore the biological function of FTO in CRC, we conducted knockdown of FTO and analyzed changes in proliferation, migration, and invasion of cultured cells in vitro and in tumor progression in vivo." (PMID 36874096, 2023). "The hypoxic tumor microenvironment reduces FTO protein expression by increasing serine/threonine kinase receptor-associated protein (STRAP)-mediated ubiquitination and facilitates CRC metastasis." (PMID 37391814, 2023). "In mice treated with gemcitabine, FTO knockdown in CFPAC-GM cells also reduced tumor growth in vivo." (PMID 37605223, 2023). "MA2, an FTO inhibitor, displayed an intrinsic anti-tumor activity with m6A methylation increasing and cell growth inhibited." (PMID 37437245, 2023). "A recent intriguing finding shows that R-2HG also displays a broad and intrinsic anti-tumor activity in leukemia and glioma by targeting FTO." (PMID 37192910, 2023). "Several small molecule inhibitors of FTO have been developed and reported to exhibit anti-tumor efficacy." (PMID 37365312, 2023). "Lentivirus knockdown of FTO in HCT116 cells (shFTO) mitigated in vivo tumor proliferation and in vitro demethylase activity, cell growth, migration and invasion compared to shScr controls (p< 0.01)." (PMID 36874096, 2023). "Although FTO has been recognized as an oncogene in several cancers, research indicating FTO as a tumor-suppressive gene also demonstrated that the expression level of FTO was remarkably downregulated within several tumors." (PMID 36718644, 2023). "The mRNA content of FTO was significantly increased in tumor tissue samples compared with the lv-NC group." (PMID 36718644, 2023). "Firstly, it is worth noting that ALKBH5 and FTO act as oncogenes or tumor suppressors in some cancers." (PMID 37007161, 2023). "Another FTO inhibitor, Dac51, restrains the glycolytic capacity of tumor cells by dampening FTO-mediated demethylation on Jun mRNA and Cebpb mRNA." (PMID 36810108, 2023). "Similar results were found in both solid and hematologic tumors, so we suggest that m6A, especially FTO, regulates chemotherapy resistance and recurrence in tumor." (PMID 37402730, 2023). "R-2-hydroxyglutaric acid (R-2HG) targets binding to FTO to inhibit demethylase activity and anti-tumour effects of 2HG in inhibiting the proliferation/survival of FTO-high cancer cells by targeting FTO/m6A/MYC/CEBPA signalling." (PMID 37194218, 2023). "FTO dysregulation was recently reported to affect the expression of tumour-derived immunosuppressive molecules." (PMID 36859310, 2023). "Our recent work that identified the role of FTO in promoting tumor glycolysis and restricting T-cell responses, and developed the novel FTO inhibitor Dac51 which can increase CD8+ T-cell infiltration in tumors as part of the host adaptive immune response." (PMID 39872548, 2023). "The overall aim of this work was to assess the role of FTO in CRC as it pertains to tumor progression." (PMID 36874096, 2023).
tumor (continued). "By interfering glycolytic activity in tumors, FTO knockdown elevated the antitumor efficacy of tumor-infiltrating lymphocytes (TILs) and inhibited tumor growth in vivo." (PMID 36810108, 2023). "FTO, the first demethylase identified in m6A modification, plays an important role in tumor progression and adipogenesis regulation." (PMID 37626050, 2023). "For example, the treatment of mice with R-2-hydroxyglutarate (R-2HG), a FTO inhibitor, can inhibit FTO demethylase activity, thus increasing the overall m6A levels and leading to anti-tumor effects in vivo." (PMID 37714846, 2023). "Among the four studies discussed in detail in the subsequent sections, two identified FTO as carcinogenic, whereas the other two suggested that it is a carcinogenic tumour suppressor." (PMID 37284313, 2023). "Mice treated by the FTO small-molecule inhibitors FB23-2 had smaller tumor size and longer survival time." (PMID 37701836, 2023). "The self-renewal and tumor formation ability of ovarian CSCs was decreased after overexpression of FTO." (PMID 37007137, 2023). "Depending on the context, FTO is believed to play both tumour-suppressing and cancer-promoting roles in an m6A-dependent manner in solid tumours." (PMID 37284313, 2023). "Further studies found that in VHL-deficient ccRCC, FTO promoted the expression of PGC-1α through demethylation modification, restored mitochondrial activity and inhibited tumor growth." (PMID 37865763, 2023). "The upregulated expression of FTO can significantly decrease cell proliferation and invasion; therefore, FTO can exhibit a tumour-suppressing effect on BC." (PMID 37284313, 2023). "As an m6A eraser protein, FTO has been reported to regulate tumor progression by inhibiting the m6A modification of some oncogenes." (PMID 38057853, 2023). "Dac51, as a small, potent FTO inhibitor, has been shown to inactivate the activity of FTO and synergize with the checkpoint blockade for better tumor control." (PMID 37175660, 2023). "Alterations in the expression of m6A writers (i.e. METTL3 and METTL14), erasers (i.e. FTO) or readers (i.e. YTHDC2 and YTHDF1), for example, are associated with tumor-suppressive or tumor-promoting scenarios." (PMID 36866275, 2023). "Overexpression of FTO in VHL-deficient RCC restored mitochondrial activity, induced oxidative stress and ROS production, and restrained tumour proliferation by increasing the expression of PGC-1α." (PMID 37284313, 2023). "It is demonstrated that D-2HG regulates the FTO/m6A/c-MYC/CEBPA signaling axis to exert antineoplastic effects by suppressing the growth and proliferation of tumor cells through FTO overexpression." (PMID 38072944, 2023). "Except for ALKBH5, related studies have reported the role of some m6A regulators, such as METTL3 and FTO, in the induction of tumour radiation resistance." (PMID 36792369, 2023). "For example, FTO protein is highly expressed in tumor samples of NSCLC patients and it can mediate the reduction of m6A modification induced by arsenic in A3B, resulting in increased expression of A3B." (PMID 38094306, 2023). "FTO is commonly downregulated in PCa tissues and cell lines, and patients with lower FTO expression have more advanced tumor stages and higher Gleason scores." (PMID 38117350, 2023). "This study also found that the tumor‐suppressive ubiquitin ligase Nedd4l was a gene target of FTO in this context." (PMID 35560957, 2023). "Some small molecule inhibitors of FTO can exert effective anti-tumor effects by making cancer cells sensitive to the cytotoxicity of T cells." (PMID 37714846, 2023). "Mechanistically, FTO acts as a tumor suppressor by inhibiting MTA1 expression, recognized by the m6A reader IGF2BP2, in an m6A-dependent manner." (PMID 37580808, 2023). "Tumor m6A research has recently gained attention, and the levels of FTO, METTL3, and YTHDC1 were significantly higher in the high-risk group compared to the low-risk group." (PMID 36968601, 2023).
tumor (continued). "On day 28, mice were sacrificed under anesthesia, and tumor weight was examined; FTO overexpression significantly decreased the tumor weight." (PMID 36718644, 2023). "One report demonstrated that omeprazole strengthens the activation of mTORC1 signaling by decreasing FTO expression in GC, restoring the chemosensitivity of tumor cells to chemotherapeutic drugs." (PMID 37443100, 2023). "Instead of acting in a manner dependent on the HIF-induced proangiogenic effect, FTO targets the glutamine transporter SLC1A5, modulating metabolic reprogramming and maintaining the survival of VHL-deficient tumour cells." (PMID 36859310, 2023). "Binary logistic regression analysis identified tumor stage as an independent factor influencing FTO levels in BC." (PMID 37861518, 2023). "FTO partially promoted the anti-tumor properties of ccRCC by decreasing m6A levels of PPARγ coactivator (PGC)‐1α mRNA transcripts and therefore increasing PGC-1α expression." (PMID 36718644, 2023). "This, therefore, suggests that high levels of FTO maintains the self-renewal ability of tumour cells through the stabilisation of oncogenes, consistent with other studies." (PMID 37444417, 2023). "As a kind of m6A demethylase, the role of FTO in various tumours has been confirmed recently, such as glioblastoma, leukemia, and ovarian cancer." (PMID 37284313, 2023). "Given the tumor-suppressive role of FTO in TC, combination of FTO activators with existing cancer therapies, such as chemotherapy, radiotherapy and immunotherapy, holds promising clinical application significance in TC patients." (PMID 37915103, 2023). "FTO inhibition by the small molecule Dac51 removes metabolic barriers in T cells and blocks tumour immune evasion through glycolytic reprogramming; moreover, Dac51 treatment is synergistic with anti-PD-L1 therapy." (PMID 36859310, 2023). "Contrary to the results obtained from the stable FTO knockdown, the overexpression of FTO gene promoted the growth of transplanted tumors in mice and shortened the survival of the tumor-bearing mice." (PMID 35568876, 2022). "PCa patients with tumor diameter < 3 cm expressed FTO at a notably higher level than those with a tumor diameter ≥ of 3 cm." (PMID 34787056, 2022). "Findings from in vivo experiments showed that knockdown of FTO significantly increased K1 tumor growth and tumor weight in xenograft mouse models." (PMID 35090515, 2022). "Consistent with in vitro observations, tumor growth size and weight were significantly decreased in FTO silenced groups compared with scrambled groups." (PMID 35422475, 2022). "Through CCK-8, scratch test, transwell migration, invasion experiments, apoptosis tests, and tumor formation tests in nude mice model, over-expression of FTO was reported to reduce the tumor growth of PTC, cell proliferation, migration, and invasion." (PMID 35721711, 2022). "In conclusion, this paper reveals the tumor-suppressive properties of FTO in the development of PTC." (PMID 35721711, 2022). "From above all, METTL3, YTHDF1/2/3, ALKBH5 play positive role in the occurrence and development of OC, while FTO is a tumor suppressor." (PMID 35813486, 2022). "WNT/β-linked protein promotes m6A modification of c-Myc mRNA and supports tumor cell glycolysis and progression by inhibiting expression of FTO, a m6A demethylase." (PMID 35794625, 2022). "Multiple m6A methylation regulators have been shown to be associated with prognosis of different tumor types, including METTL3, WTAP, IGF2BP, FTO, and YTHDF." (PMID 35794625, 2022). "Tumor growth was impaired in FTO downregulation mice compared to WT mice, as illustrated by bioluminescence imaging." (PMID 36263177, 2022).
tumor (continued). "FTO elevated in tumor adjacent tissues of the liver and contributed to the m6A mRNA demethylation of IL-17RA, which led to the elevated translational regulation of IL-17RA, exacerbating liver inflammation and worsening liver function." (PMID 36172147, 2022). "As seen by IHC staining, compared with the negative control, the expression of Ki-67 proliferation antigen in tumor tissues with FTO knockdown was significantly stronger." (PMID 35397614, 2022). "Increasing evidence has emerged to reveal the complex biological functions of FTO, especially tumor initiation and progression." (PMID 35311620, 2022). "FTO knockdown significantly curbs the expression of ferroptosis in PTC cells while also promoting tumor progression." (PMID 35721711, 2022). "Next, we implanted a subcutaneous pancreatic xenograft tumor to further determine the oncogenic roles of FTO in vivo." (PMID 35422475, 2022). "FTO-mediated m6A demethylation in tumor cells enhances transcription factors, such as c-Jun, JunB and C/EBPβ, thereby inducing hypoxia-mediated glycolytic metabolism and suppressing CD8+ T cell function." (PMID 35794625, 2022). "PET-CT findings showed that glucose uptake in xenograft mouse tumor model was significantly increased after FTO knockdown compared with the control." (PMID 35090515, 2022). "18F-FDG PET scan analysis showed that FTO knockdown significantly promoted tumor growth and glucose uptake in xenograft mouse tumor model in vivo." (PMID 35090515, 2022). "Thereafter, we analyzed the relationships between gender, age, pathological grade, tumor stage, lymph node metastasis, tumor size, and the FTO expression level." (PMID 35568876, 2022). "Based on the IHC score, FTO was expressed at higher levels in tumor tissues compared with normal tissues." (PMID 35422475, 2022). "Downregulation of FTO facilitated the proliferation, migration, invasion and tumor growth of PCa cells." (PMID 34787056, 2022). "Further immunohistochemistry assays showed that FTO knockdown inhibited the expression of Vimentin and E-cadherin, indicating an inhibiting effect of tumor metastasis, whereas ERBB2 has a reverse effect." (PMID 35524932, 2022). "Compared to the control groups, FTO knockdown in KYSE150 cells effectively inhibited the tumor formation and growth." (PMID 35524932, 2022). "Previous studies showed that the expression of m6A writers (METTL3, RBM15, WTAP), eraser (FTO, ALKBH5) and reader (YTHDF3, YTHDC2) was associated with pathological stage, tumor stage, andprognosis of patients with GC." (PMID 35977935, 2022). "In vitro experiments have similarly shown that FTO is a tumor-promoting factor that activates miR-181b-3p/ARL5B signaling leading to tumor migration." (PMID 36035182, 2022). "Correlations of the EMD score with tumor mutation burden, tumor purity, aneuploidy score, tumorigenic pathways, TME characteristics, and FTO/HDAC1 ratio were measured." (PMID 35600848, 2022). "FTO inhibited autophagy of ccRCC cells and promoted tumor progression through an m6A-IGF2BP2-dependent mechanism, and SIK2 was their m6A target." (PMID 36360294, 2022). "Overexpression of FTO promotes tumor cell growth, while knockdown of FTO significantly increases tumor cells’ response to INF-γ and anti PD-L1 treatment sensitivity." (PMID 36561529, 2022). "The m6A modification regulators (such as FTO) play important roles in the PD-1/PD-L1 inhibitor tumor immunotherapy." (PMID 35154270, 2022). "The further investigation highlighted that depletion of HDAC3 impeded tumor growth and reduced the protein synthesis of FTO/MYC, and elevated the expression of FOXA2 in nude mice." (PMID 35628623, 2022). "HE staining indicated a reduced tumor cell number and IHC analysis showed lowered Ki-67 and FTO levels in the circGPR137B group as compared with the control group." (PMID 35858900, 2022).
tumor (continued). "As well as regulating immune checkpoint genes, FTO functions as an oncogene by reprogramming the glycolytic metabolism of tumor cells; it also further inhibits CD8+ T cell activity." (PMID 35296338, 2022). "FTO promotes the growth and self-renewal of GSCs, which is required for substantial tumor progression." (PMID 36437944, 2022). "There is also an interaction between Ms, with knockdown of FTO increasing m6A methylation in key pro-tumor cell-intrinsic genes including PD-1, SOX10 and CXCR4, resulting in increased RNA decay through the reader YTHDF2." (PMID 35265626, 2022). "Expectedly, EGR2 protein expression level was significantly increased after FTO overexpression in tumor-bearing mice." (PMID 37529797, 2022). "In particular, FTO suppressed the expression of tumor suppressors, including ankyrin repeat and SOCS box containing 2 (ASB2) and retinoic acid receptor alpha (RARA) by eliminating m6A sites." (PMID 35628623, 2022). "After adjusting for some factors, such as pathological grade, gender, and so on, we found that age, tumor stage, and FTO expression levels still affected the overall survival of EC patients." (PMID 35568876, 2022). "Taken together, our findings indicated that down-regulated FTO/PHF1 axis triggered the tumor stemness features to drive progression by activating FOXM1." (PMID 35945194, 2022). "Then, the mice were sacrificed and the tumor bearing kidneys were anatomized, which indicated knockdown FTO significantly retarded tumor growth." (PMID 35961973, 2022). "In this study, based on data from the TCGA-THCA cohort, we obtained DEGs between normal and tumor tissues and identified 3 m6A-related genes (KIAA1429, RBM15, and FTO) to construct a risk model and verified its credibility." (PMID 36389678, 2022). "We examined the expression of FTO between tumor tissues and normal tissues, elucidated the effect of FTO overexpression on PCa cells, screened out target genes of FTO, and demonstrated the relationship between them." (PMID 37529797, 2022). "The demethylase FTO, an “eraser” of m6A methylation, exhibits dual effects (tumorigenesis and tumor inhibition) in disparate solid tumors." (PMID 36438800, 2022). "Collectively, our findings revealed that FTO positively regulates PHF1 expression and determined the tumor-suppressive role of FTO/PHF1 axis, thereby highlighting insights into its epigenetic remodeling mechanisms in LUAD progression and treatment." (PMID 35945194, 2022). "In contrast, a novel tumor suppressor role of the RNA demethylase FTO indicates m6A RNA modifications in the regulation of cyclic AMP signaling involved in stemness and tumor initiation." (PMID 35945194, 2022). "Heatmap analysis showed that 10 m6A regulators were significantly more highly expressed in tumour tissue than in normal tissue (p < 0.05), except for FTO and ALKBH5." (PMID 35189810, 2022). "We also constructed a tumor metastasis model by injecting FTO knockdown DU145 cells intravenously into mice to verify the effect of FTO on PCa metastasis." (PMID 35397614, 2022). "To further interrogate the role of FTO in vivo, we constructed a xenograft tumor mouse model through subcutaneously injecting FTO overexpression stable Du145 cells." (PMID 37529797, 2022). "Consistent with this idea, depleting FTO impaired the glycolytic activity of tumor cells to restore the CD8+ T cell function needed to inhibit tumor growth." (PMID 35186927, 2022). "To further confirm the downregulation of FTO mRNA levels, we used immunohistochemistry assay to identify FTO protein expression in 68 PCa samples, of which 24 have matching tumor tissues and corresponding paracancerous tissues." (PMID 35397614, 2022). "Studies also indicate that FTO is downregulated in PCa tissues and can act as a tumor suppressor to repress cell proliferation, migration and invasion." (PMID 34787056, 2022). "Collectively, these results establish that FTO-autophagy interaction is an epitranscriptional mechanism of ccRCC tumor progression." (PMID 36263177, 2022).